MTO1 (mitochondrial tRNA translation optimization 1)
Description:
Component of the GTPBP3-MTO1 complex that catalyzes the 5-taurinomethyluridine (taum(5)U) modification at the 34th wobble position (U34) of mitochondrial tRNAs (mt-tRNAs), which plays a role in mt-tRNA decoding and mitochondrial translation. Taum(5)U formation on mammalian mt-tRNA requires the presence of both GTPBP3-mediated GTPase activity and MTO1 catalytic activity.
Synonyms: CGI-02; COXPD10
Tractability: PROTAC: ubiquitination databases record sites on it; its protein half-life has been measured.
Gene: Protein-coding gene on chromosome 6 (73,461,578 to 73,509,236, forward strand). Ensembl gene ENSG00000135297.
Subcellular location: Mitochondrion
Subcellular location (Human Protein Atlas): Nucleoplasm; Cytosol
Pathways (Reactome):
Metabolism of RNA: tRNA modification in the mitochondrion
Gene Ontology:
Molecular function: RNA binding; tRNA 5-taurinomethyluridine synthase activity; flavin adenine dinucleotide binding
Biological process: mitochondrial tRNA wobble uridine modification; tRNA processing
Cellular component: GTPBP3-MTO1 complex; mitochondrion
Genetic constraint (gnomAD): Loss-of-function variants: 48 observed, 74.42 expected, observed/expected ratio (o/e) 0.65, 90% interval 0.51 to 0.82. The upper end of that interval is the gene's LOEUF score, 0.82, which puts it in group 3 of 6, group 1 being the genes least tolerant of losing a copy. Missense variants: 759 observed, 901.37 expected, observed/expected ratio (o/e) 0.84, 90% interval 0.79 to 0.89. Synonymous variants: 291 observed, 324.6 expected, observed/expected ratio (o/e) 0.9, 90% interval 0.81 to 0.99.
Gene-disease validity (ClinGen):
ClinGen rates the evidence that MTO1 causes each of these diseases.
mitochondrial disease (autosomal recessive): Definitive.
Homologues: Orthologues: chimpanzee MTO1 (99% identical), macaque MTO1 (97% identical), pig MTO1 (89% identical), dog MTO1 (89% identical), rabbit MTO1 (88% identical), rat Mto1 (85% identical), mouse Mto1 (84% identical), guinea pig MTO1 (83% identical), tropical clawed frog mto1 (61% identical), Drosophila melanogaster CG4610 (53% identical), zebrafish mto1 (49% identical), Caenorhabditis elegans mtcu-2 (46% identical).
Diseases named in the same sentence as MTO1 in open-access papers:
MTO1 is named in the same sentence as 57 diseases in open-access papers, as found by Europe PMC text mining. Sharing a sentence is not in itself a finding about the gene and the disease. The quoted sentences say what the papers report.
hypertrophic cardiomyopathy (15 papers, 2013 to 2025). A condition in which the myocardium is hypertrophied without an obvious cause. "The gene ips1 encoding a tRNA-modifying enzyme is homologous to human tRNA translation optimization-related gene (MTO1), which is linked to a mitochondrial disease characterized by hypertrophic cardiomyopathy." (PMID 37859837, 2023). "To investigate if defects in MTO1 cause the hypertrophic cardiomyopathy in vivo, we generated the mto1 knock-out (KO) zebrafish produced by genome editing using the CRISPR/Cas9 system." (PMID 33836087, 2021). "Especially, the clinical features of MTO1 deficiency included hypertrophic cardiomyopathy, lactic acidosis, and developmental delay." (PMID 33836087, 2021). "To examine if the MTO1-deficiency changed the gene expression profile for the development of hypertrophic cardiomyopathy and the deficiency of complex I and IV, we performed mRNA sequencing on hearts of WT and mto1−/− zebrafish at the age of 4–6 months." (PMID 33836087, 2021). "We then investigated if mto1−/− zebrafish recapitulated the hypertrophic cardiomyopathy phenotypes in the patients carrying the MTO1 mutations." (PMID 33836087, 2021). "An extensive review of all known MTO1 deficiency cases revealed the most common features at presentation to be lactic acidosis (LA) (21/34; 62% cases) and hypertrophic cardiomyopathy (15/34; 44% cases)." (PMID 29331171, 2018). "Hallmark features of MTO1 deficiency include hypertrophic cardiomyopathy (HCM), lactic acidosis (LA) and mild to severe global developmental delay (GDD)/intellectual disability (ID) but significant phenotypic heterogeneity exists." (PMID 29331171, 2018). "Mutations in human MTO1 have been implicated in hypertrophic cardiomyopathy and lactic acidosis; introduction of the corresponding mutations into yeast MTO1 result in a defective enzyme, which only partially rescued a Δmto1 yeast mutant." (PMID 26462863, 2016). "Another study has shown that MTO1 mutations are associated with a mitochondrial disorder characterized by hypertrophic cardiomyopathy, lactic acidosis, and MRC deficiency." (PMID 25898254, 2015). "Noteworthy, mutations affecting MTO1, an enzyme responsible for tRNA modifications that increases the accuracy and efficiency of mtDNA translation, have been found in patients with hypertrophic cardiomyopathy." (PMID 24639874, 2014). "Recently, mutations in the mitochondrial translation optimization factor 1 gene (MTO1) were identified as causative in children with hypertrophic cardiomyopathy, lactic acidosis and respiratory chain defect." (PMID 25506927, 2014). "In five additional MTO1 patients, early-onset hypertrophic cardiomyopathy and lactic acidosis associated with respiratory chain deficiency was observed as well." (PMID 25506927, 2014). "Hypertrophic cardiomyopathy seems to be the clinical hallmark of MTO1 mutations, although in the present study most of the patients were preselected on the basis of cardiac symptoms." (PMID 23929671, 2013). "Our study suggests that despite deficiencies in either MTO1 or GTPBP3 cause hypertrophic cardiomyopathy with lactic acidosis, the underlying metabolic signalling in patient cells may be different (see Supplementary Discussion)." (PMID 29348686, 2018). "This study confirmed that MTO1 mutations are associated with a mitochondrial disorder, characterized by hypertrophic cardiomyopathy, lactic acidosis, and MRC deficiency, albeit with a broad range of severity and frequent involvement of brain, possibly depending on the treatment." (PMID 23929671, 2013). "Our findings highlighted the critical role of MTO1 in mitochondrial transcript maturation and their pathological consequences in hypertrophic cardiomyopathy." (PMID 33836087, 2021). "Previous investigations showed that pathogenic variants in MTO1 for the biosynthesis of τm5U of tRNAGlu, tRNAGln, tRNALys, tRNATrp and tRNALeu(UUR) were associated with hypertrophic cardiomyopathy (HCM)." (PMID 33836087, 2021).
hypertrophic cardiomyopathy (continued). "They include MELAS (mitochondrial encephalomyopathy and lactic acidosis with stroke-like episodes), MERRF (myoclonic epilepsy and ragged-red fiber), TRMU-dependent acute infantile liver failure and hypertrophic cardiomyopathies dependent on MTO1 and GTPBP3." (PMID 26642043, 2015). "Like MTO1 mutations, GTPBP3 mutations (MIM 608536) are mostly associated with hypertrophic cardiomyopathy, lactic acidosis, and combined respiratory chain deficiency." (PMID 26642043, 2015). "We present here the identification of five additional MTO1 mutant subjects (two couples of siblings, and a sporadic case) who also present with hypertrophic cardiomyopathy and lactic acidosis, thus, strengthening a consistent genotype/phenotype correlation." (PMID 23929671, 2013). "MTO1 mutations cause combined oxidative phosphorylation deficiency 10 (COXPD10), presenting with infantile hypertrophic cardiomyopathy and lactic acidosis, while GTPBP3 mutations cause COXPD23, characterized by early childhood hypertrophic cardiomyopathy and neurological symptoms." (PMID 41465450, 2025). "Using mto1 knock-out zebrafish generated with CRISPR/Cas9 system, we demonstrated the profound impacts of Mto1 deficiency on mitochondrial transcript maturation contributing to the pathogenesis of hypertrophic cardiomyopathy." (PMID 33836087, 2021). "The mto1 mutants exhibited hypertrophic cardiomyopathy in adult zebrafish." (PMID 33836087, 2021). "However, the lack of MTO1-deficiency animal model makes us difficult to elucidate the pathogenic mechanism underlying the MTO1-deficiency-manifesting hypertrophic cardiomyopathy." (PMID 33836087, 2021). "In brief, we present here C. elegans models for the human diseases associated with hypomodification at position 2 and 5 of U34 in a mt-tRNA set, which exhibit different phenotypes: liver failure (TRMU) or hypertrophic cardiomyopathy (GTPBP3 and MTO1)." (PMID 28732077, 2017).
lactic acidosis (13 papers, 2013 to 2025). Metabolic acidosis characterized by the accumulation of lactate in the body. "Several patients have been identified as being affected by hypertrophic cardiomyopathy and lactic acidosis due to mutations in the MTO1 gene." (PMID 36768505, 2023). "Recently, the first human mutations in MTO1 were identified by exome sequencing in two siblings and a third unrelated individual with infantile hypertrophic cardiomyopathy, lactic acidosis and a respiratory chain defect (MIM 614667)." (PMID 25506927, 2014). "A current example is the identification of MTO1 mutations in infantile hypertrophic cardiomyopathy and lactic acidosis." (PMID 25506927, 2014). "In both cases, the uncoupling is expected to result in lactic acidosis, a common clinical trait present in MTO1 and GTPBP3 patients." (PMID 29348686, 2018). "Mutations of MTO1 (MIM #614667) cause infantile hypertrophic cardiomyopathy, lactic acidosis and, in some patients, neurological features." (PMID 26642043, 2015).
hepatocellular carcinoma (7 papers, 2019 to 2025). A malignant tumor that arises from hepatocytes. "For instance, circ‐MTO1 expression is associated with longer OS in patients with colorectal cancer and hepatocellular carcinoma." (PMID 35478417, 2022). "Recently, circMTO1 (a circRNA derived from MTO1 gene), identified as a tumor suppressor, has been shown to contribute to the suppression of hepatocellular carcinoma." (PMID 31148365, 2019). "The circular RNA MTO1 (circMTO1) originates from exons 2 and 3 of the mitochondrial tRNA translation optimization 1 (MTO1) gene with a 318bp splice length, and was first reported in hepatocellular carcinoma." (PMID 34277605, 2021). "Besides this, it was also reported that circ-MTO1 suppresses hepatocellular carcinoma progression by acting as a sponge for miR-9 in hepatocellular carcinoma tissues." (PMID 32692763, 2020). "CircRNA MTO1 directly sponges to miRNA-9 to inhibit the progression of hepatocellular carcinoma." (PMID 32760224, 2020). "Recently, cMTO1 (a circRNA derived from MTO1 gene, hsa_circ_0007874) has been demonstrated to act as a tumor suppressor in hepatocellular carcinoma (HCC)." (PMID 32850833, 2020).
breast carcinoma (6 papers, 2013 to 2025). "However, exceptions were observed: mitochondrial tRNA translation optimization 1 (MTO1) was identified as a risk factor in breast cancer, while COX5B was associated with increased risk in endometrial cancer." (PMID 40396172, 2025). "For example, circRNA MTO1 was down-regulated in breast cancer and HCC." (PMID 33041662, 2020). "Moreover, the promotion of circRNA MTO1 suppressed cell viability, promoted cell cytotoxicity and reversed monastrol resistance in breast cancer." (PMID 33041662, 2020). "Recently, the MTO1 gene was also reported to play a role in breast cancer tissues and cells." (PMID 25898254, 2015). "Detailed understanding of the mechanism through which estrogen and tamoxifen affect MTO1 and MRPL41 transcription is expected to provide new insights into breast cancer progression and suggest new strategies for delaying or reversing this process." (PMID 24160266, 2013). "In this study, we examined the regulation of MTO1 and MRPL41 in ER+ and ER- breast cancer cells, and also in cells treated with estradiol (E2) and tamoxifen." (PMID 24160266, 2013). "The present results indicate that the two mitochondrial genes, MTO1 and MRPL41, were differentially regulated in breast cancer such that they showed the opposite response to E2, tamoxifen, and TSA." (PMID 24160266, 2013). "Taken together, identifying the link between epigenetic regulation and MTO1 and MTRL41 expression may represent novel breast cancer markers that are regulated in opposite ways by ER modulators." (PMID 24160266, 2013). "Moreover, the histone deacetylase inhibitor trichostatin A (TSA) increased MTO1 and MRPL41 expression in ER- and ER+ breast cancer cells, respectively." (PMID 24160266, 2013).
cardiomyopathy (6 papers, 2013 to 2025). A disease of the heart muscle or myocardium proper. "Mutations in the genes coding for GTPBP3 and MTO1 lead to severe mitochondrial diseases, including cardiomyopathy, encephalopathy, lactic acidosis, optic neuropathy, and cognitive disability." (PMID 40884400, 2025). "Additionally, MnmG residue G55 within this interaction region corresponds to the site of a cardiomyopathy-associated mutation in human MTO1 (G85R)." (PMID 40884400, 2025). "Although in MTO1 deficiency the cardiomyopathy is usually hypertrophic, one patient developed a dilated form (patient 12) which we recognize may be a progression from HCM." (PMID 29331171, 2018). "Twelve of the 52 mouse models identified with cardiomyopathy (Acadv1, Fxn, Mto1, Taco1, Hmgcs2, Mpv17, Opa1, Pnpla8, Tmem126b, Gpd2, Mpv17, Micu1) showed that the presence of cardiomyopathy can be dependent on the degree of stress." (PMID 37103033, 2023). "A further four cases of MTO1 deficiency without cardiomyopathy at ages 0.66 to 22 years, one published and three unpublished, were identified in our review." (PMID 29331171, 2018). "The milder phenotype in the mice (less pronounced cardiomyopathy, normal survival) may be due to residual expression of full-length Mto1 transcripts in our knockdown mice." (PMID 25506927, 2014).
MELAS (6 papers, 2009 to 2025). "The third gene identified and associated with MELAS was MTO1 from which there were n = 2 separate heterozygous variants ENST00000370300.4 c.350G > A p.Arg117His (rs763571382) and ENST00000370300.4 c.1505G > A p.Arg502His (rs201544686)." (PMID 35699875, 2022). "The proposed mechanism in MELAS that causes this induction of miR-9/9* and subsequent downregulation of MTO1 relates to oxidative stress and increased levels of intracellular Ca2+ and reactive oxygen species (ROS)." (PMID 35699875, 2022). "Furthermore, MELAS patients with the m.3243G > A variant have been found to have a decreased expression of MTO1 due to the inducing miR-9/9*." (PMID 35699875, 2022). "Patient 6 was diagnosed with MELAS after he had been implanted with an ICD for SCD risk prevention and Patient 7 carried a bi-allelic variant in MTO1." (PMID 37240454, 2023). "It would be interesting to investigate the cellular effects caused by the variants in DGR023 and DGR025 to see if this correlates with a decreased expression or activity of MTO1 resulting in a phenotype mimicking MELAS or related to CSVD." (PMID 35699875, 2022).
deafness (3 papers, 2010 to 2015). An inherited or acquired condition characterized by the complete loss of the ability to hear from one or both ears. "In a study of deafness, the MTO1 gene was defined as one nuclear modifier gene which interacted with other factors, such as mitochondrial mutations, to affect the deafness phenotype." (PMID 25898254, 2015). "Using this method, the DFNM1 locus, a modifier of DFNB26-linked deafness was identified and the deafness phenotype associated with the 1555A>G mutation in MTRNR1 was shown to be modified by three different genes: MTO1, TFB1M and GTPBP3." (PMID 21119891, 2010).
gastric cancer (3 papers, 2021 to 2024). A primary or metastatic malignant neoplasm involving the stomach. "In gastric cancer patients, tumor circ‐MTO1 high expression was associated with better accumulating DFS (p = 0.027)." (PMID 35478417, 2022). "For example, the circular RNA MTO1 slows the progression of gastric cancer by increasing Prostate Apoptosis Response-4 protein (PAWR) levels by sponging miR-199a-3p." (PMID 39293372, 2024). "Secondly, specific mechanism about how circ‐MTO1 regulated gastric cancer progression was still unclear and was required to be extensively explored in the future." (PMID 35478417, 2022). "As for gastric cancer, previous studies exhibit that circ‐MTO1 suppresses its development and progression by regulating microRNA (miR)‐3200‐5p/phosphatidylethanolamine binding protein 1 (PEBP1) axis and miR‐199a‐3p/pro‐apoptotic WT1 regulator (PAWR) axis." (PMID 35478417, 2022). "Circ‐MTO1 expression was obviously lower in tumor tissue than in adjacent tissue of gastric cancer patients (p < 0.001)." (PMID 35478417, 2022). "This study aimed to assess the expression of circ‐MTO1, its correlation with clinical characteristics, and prognosis in postoperative patients with gastric cancer, as well as the effect of circ‐MTO1 on oxaliplatin sensitivity in gastric cancer cell lines." (PMID 35478417, 2022). "The main findings were listed as follows: 1) Circ‐MTO1 was down‐regulated in tumor tissue compared with adjacent tissue of gastric cancer patients." (PMID 35478417, 2022). "Circ‐MTO1 in tumor and adjacent tissues of 97 gastric cancer patients undergoing resection were examined by reverse transcription‐quantitative polymerase chain reaction." (PMID 35478417, 2022). "Circular‐mitochondrial translation optimization 1 (circ‐MTO1) inhibits the progression of gastric cancer by regulating the growth, apoptosis, and invasion of tumor cells." (PMID 35478417, 2022). "Since circ‐MTO1 independently correlated with PFS, we further explored the effect of circ‐MTO1 on oxaliplatin sensitivity in gastric cancer cell lines; then, plasmid transfection was conducted in HGC‐27 and NCI‐N87 cells followed by the oxaliplatin treatment." (PMID 35478417, 2022). "Lastly, in gastric cancer cells, OE‐circ‐MTO1 apparently decreased relative cell viabilities at oxaliplatin concentrations of 0.4, 0.8, 1.6, and 3.2 μM (all P<0.05)." (PMID 35478417, 2022). "Circ‐MTO1 in tumor and adjacent tissues of 97 gastric cancer patients undergoing resection was examined by reverse transcription‐quantitative polymerase chain reaction." (PMID 35478417, 2022). "This could be supported by the result that circ‐MTO1 increased the sensitivity of gastric cancer cell lines to oxaliplatin in this study." (PMID 35478417, 2022). "This study aimed to assess circ‐MTO1 expression and its correlation with clinical features and prognosis in gastric cancer patients, as well as the effect of circ‐MTO1 on the sensitivity to chemotherapy in gastric cancer cells." (PMID 35478417, 2022). "However, the clinical potential of circ‐MTO1 as a biomarker for gastric cancer patients remains to be further evaluated." (PMID 35478417, 2022). "Circ‐MTO1 correlates with less lymph node metastasis, prolonged DFS, and improved chemotherapy sensitivity in gastric cancer." (PMID 35478417, 2022). "Conclusively, circ‐MTO1 correlates with less lymph node metastasis, prolonged DFS, and increased chemotherapy sensitivity in gastric cancer." (PMID 35478417, 2022). "The current study also displayed that tumor circ‐MTO1 was correlated with prolonged DFS and was an independent factor affecting DFS in gastric cancer patients." (PMID 35478417, 2022). "Partly in line with these reports, our study presented that tumor circ‐MTO1 was correlated with less severe lymph node metastasis and clinical TNM stage in gastric cancer patients." (PMID 35478417, 2022). "Circ‐MTO1 high expression was independently correlated with prolonged DFS, but was not correlated with OS in gastric cancer patients." (PMID 35478417, 2022).
colorectal cancer (2 papers, 2021 to 2022). A primary or metastatic malignant neoplasm that affects the colon or rectum. "For example, a study shows that insufficient circ‐MTO1 expression is associated with advanced lymph node metastasis and TNM stage in colorectal cancer patients." (PMID 35478417, 2022). "Clinically, insufficient circ‐MTO1 expression is correlated with frequent lymph node metastasis, advanced TNM stage, and shortened overall survival (OS) in patients with colorectal cancer." (PMID 35478417, 2022).